WWP1 (WW domain containing E3 ubiquitin protein ligase 1)
Diseases named in the same sentence as WWP1 in open-access papers (continued):
Sharing a sentence is not in itself a finding about the gene and the disease.
hepatocellular carcinoma (8 papers, 2015 to 2024). A malignant tumor that arises from hepatocytes. "WWP1 acts as a critical oncogene in many solid tumors, including breast, prostate, and hepatocellular cancers, and in hematological malignancies, specifically in AML." (PMID 38129384, 2023). "In the present study, we investigated the expression and prognostic role of WWP1 in primary hepatocellular carcinoma (HCC) using cell lines and 149 archived HCC samples." (PMID 26506518, 2015). "Therefore, further analysis of WWP1 will improve understanding of not only obesity‐related metabolic dysfunction but also hepatic steatosis‐related pathologies, such as cirrhosis and hepatocellular carcinoma." (PMID 37032433, 2023). "WWP1 expression at both mRNA and protein levels was elevated in hepatocellular carcinoma (HCC) specimens compared with adjacent non-tumor hepatic tissues." (PMID 34226507, 2021). "However, the role of WWP1 in hepatocellular carcinoma(HCC) is not clear." (PMID 26506518, 2015).
Sepsis (8 papers, 2022 to 2025). Sepsis is defined as life-threatening organ dysfunction caused by a dysregulated host response to infection. "Complementarily, Zhang reported that in a mouse model of sepsis, YTHDF1 can inhibit pyroptosis of cells and alleviate the damage caused by sepsis by promoting the ubiquitination of NLRP3 and upregulating the WW domain-containing E3 ubiquitin ligase 1 (Wwp1)." (PMID 41341492, 2025). "YTHDF1 alleviated sepsis by upregulating the transcription of WWP1 to induce NLRP3 ubiquitination and inhibit caspase-1-dependent pyroptosis." (PMID 38022612, 2023). "Of note, the bioinformatics prediction in the current study found WW domain containing E3 ubiquitin protein ligase 1 (WWP1) to be a differential gene in sepsis which can be recognized by YTHDF1." (PMID 35508474, 2022). "To conclude, the regulatory role of WWP1 in sepsis was achieved through its mediation of NLRP3 inflammasomes and caspase-1-dependent pyroptosis." (PMID 35508474, 2022). "Mechanistically, our study further demonstrated that WWP1 suppressed caspase-1-dependent pyroptosis by promoting NLRP3 ubiquitination in sepsis." (PMID 35508474, 2022). "Based on the results obtained in the current study, a conclusion is reached that YTHDF1 promotes NLRP3 ubiquitination by upregulating WWP1, thereby inhibiting caspase-1-dependent pyroptosis, which contributes to attenuation of sepsis." (PMID 35508474, 2022). "In order to further explore the molecular mechanism of WWP1 in sepsis, we treated RAW264.7 cells with LPS and ATP to construct an in vitro cell model of sepsis." (PMID 35508474, 2022). "To further explore the role of WWP1 in the regulation of sepsis, we first established a sepsis mouse model through CLP, and analyzed the survival rate of the mice." (PMID 35508474, 2022). "WWP1 is a differentially expressed gene in sepsis recognized by YTH domain-containing family protein 1 (YTHDF1), an RNA-binding protein specialized in recognizing m6A, a dynamic mRNA modification that plays a pivotal role in governing protein expression across various post-transcriptional stages." (PMID 38129384, 2023). "WWP1 might also contribute to YTHDF1-mediated alleviation of sepsis by promoting NLRP3 ubiquitination." (PMID 38129384, 2023). "Peripheral blood of patients with sepsis was collected to determine WWP1 and YTHDF1 expression." (PMID 35508474, 2022). "It has been reported that YTHDF1 can promote the translation of target transcripts, indicating that YTHDF1 may alleviate sepsis by promoting WWP1 expression." (PMID 35508474, 2022). "RT-qPCR results confirmed that WWP1 was downregulated in patients with sepsis." (PMID 35508474, 2022). "This study clarified the regulatory role of YTHDF1 in sepsis with the involvement of WWP1/NLRP3/caspase-1 axis and found that YTHDF1 could upregulate WWP1 to enhance NLRP3 ubiquitination and restrict caspase-1-dependent pyroptosis in sepsis." (PMID 35508474, 2022). "Interestingly, in the current study, it was found through rmbase-based analysis in combination with RT-qPCR and Western blot assay that YTHDF1 could promote the expression of WWP1 in sepsis." (PMID 35508474, 2022). "It was noted that WWP1 and YTHDF1 were downregulated in clinical sepsis samples, LPS + ATP-treated RAW264.7 cells, and CLP-induced mice." (PMID 35508474, 2022). "In order to further investigate the effect of YTHDF1/WWP1/NLRP3/caspase-1 axis on sepsis, RAW264.7 cells were transfected with oe-NC/oe-YTHDF1, or sh-NC/sh-WWP1." (PMID 35508474, 2022). "In the first place, the present study revealed that WWP1 and YTHDF1 were downregulated in sepsis." (PMID 35508474, 2022). "YTHDF1 can positively regulated the expression of WW domain containing E3 ubiquitin protein ligase 1 (WWP1) expression through RNA modifications, which increases the ubiquitination of NLRP3 and subsequetly decreases NLRP3 expression levels, thereby alleviating sepsis." (PMID 41373022, 2025).
glioma (7 papers, 2019 to 2025). A benign or malignant brain and spinal cord tumor that arises from glial cells (astrocytes, oligodendrocytes, ependymal cells). "WWP1 mRNA expression was negatively associated with miR-30a-5p expression in glioma specimens." (PMID 34226507, 2021). "The potential for targeting WWP1 in glioma therapy remains a promising area for future investigation." (PMID 39949609, 2024). "Although these findings suggest a potential role for WWP1 in glioma development and indicate its promise as a therapeutic target, further direct experimental evidence is required to confirm its causal involvement in glioma progression." (PMID 39949609, 2024). "In glioma cell lines (U87, U251), decreased WWP1 mRNA levels correlate with increased miR-30a-5p and phosphorylated p65 levels." (PMID 39949609, 2024). "For instance, WWP1 can suppress glioma proliferation by inhibiting the phosphorylation of the p65 subunit of NF-kB, thereby decreasing NF-kB-mediated miR-30a-5p transcription." (PMID 38129384, 2023). "In contrast, oncogenic miR-30a-5p targets the 3’-UTR of WWP1 to promote cell proliferation, migration, and invasion in glioma." (PMID 38129384, 2023). "A recent investigation demonstrates that both mRNA and protein levels of WWP1 significantly decline in human glioma tissues and cell lines, compared with normal brain tissues and astrocytes, respectively." (PMID 34712671, 2021). "WWP1 overexpression suppressed cell malignant behaviors and tumor growth in glioma xenograft mouse model." (PMID 34226507, 2021). "In contrast, WWP1 overexpression reduced miR-30a-5p expression by inhibiting NF-κB, thereby inhibiting the vicious behavior of glioma cells." (PMID 31320543, 2019). "Additionally, upregulation of WWP1 has been shown to suppress malignant phenotypes in glioma cells in vitro and inhibit tumor growth in vivo." (PMID 40280416, 2025). "Upregulation of miR-30a-5p may lead to this downregulation of WWP1 at mRNA level, and consequently promotes glioma cell proliferation, migration, and invasion via an unknown mechanism." (PMID 34712671, 2021). "One group demonstrated that WWP1 is a direct target of miR-30a-5p in glioma." (PMID 34226507, 2021). "Moreover, NF-kappaB p65 upregulated the expression of miR-30a-5p via interaction of NF-kappaB RelA subunit and the miR-30a-5p promoter region, leading to inhibition of WWP1 and promoting glioma malignant phenotype." (PMID 34226507, 2021). "Interestingly, WWP1 upregulation also reduced miR-30a-5p expression and inhibited p65 expression in glioma cells." (PMID 34226507, 2021). "Moreover, overexpression of NF-κB increased the expression of miR-30a-5p, inhibited the expression of its target gene WWP1, and promoted the malignant behavior of glioma cells." (PMID 31320543, 2019). "Notably, miR-30a-5p promoted glioma cell proliferation, migration, and invasion by targeting WWP1." (PMID 39949609, 2024). "Therefore, a miR-30a-5p/WWP1/p65 feedback loop was exhibited to regulate development of glioma." (PMID 34226507, 2021). "For instance, in glioma tissues, decreased WWP1 levels correlated with increased miR-30a-5p and p65 phosphorylation levels, suggesting a negative correlation between WWP1 mRNA and miR-30a-5p expression." (PMID 39949609, 2024).
Hyperglycemia (7 papers, 2020 to 2024). An increased concentration of glucose in the blood. "In addition, it has been reported that hyperglycemia is linked with muscle atrophy via a WW domain containing E3 ubiquitin protein ligase 1 (WWP1)/Krüppel-like factor 15 (KLF15) pathway." (PMID 32784808, 2020). "WWP1 is an endogenous E3 ligase that is known to prevent muscle atrophy during hyperglycemia by particularly targeting the Krüppel-like factor 15 (KLF15) protein, leading to the UPP-dependent KLF15 degradation." (PMID 39433511, 2024). "Hyperglycemia results in the downregulation of WWP1, thereby preventing WWP1-mediated degradation of KLF15 in skeletal muscle of old diabetic animals." (PMID 38129384, 2023). "Hyperglycemia inhibits degradation of KLF15 via downregulation of WWP1 and increased KLF15 promotes proteolysis via upregulation of atrogin-1 and MuRF1." (PMID 32784808, 2020). "Hence, the intricate relationship between hyperglycaemia, WWP1/KLF15 and diabetes-related WWP1 downregulation underscores the complex factors contributing to skeletal muscle atrophy, shedding light on potential mechanisms across various contexts." (PMID 38129384, 2023). "We recently showed that the abundance of KLF15 in skeletal muscle is increased in response to hyperglycemia as a result of suppression of its ubiquitination by the E3 ubiquitin ligase WWP1, which in turn contributes to the development of skeletal muscle atrophy in diabetes mellitus." (PMID 35290243, 2022). "Various molecular pathways have been identified in which high glucose levels play a significant role in hyperglycemia-induced muscle degradation, with the key role of the ubiquitin-proteasome pathway (UPP) and WWP1/KLF15 pathway." (PMID 39433511, 2024). "Hyperglycemia was recently shown to promote skeletal muscle atrophy via the induction of KLF15, which is regulated by WW domain-containing E3 ubiquitin protein ligase 1 (WWP1) or cAMP-PKA/CREB signaling." (PMID 34571935, 2021). "Furthermore, studies in mice have shown that hyperglycemia, a central disease of diabetes, promotes muscle atrophy via the WWP1/KLF15 pathway and that in mice lacking KLF15, specifically in the skeletal muscle, hyperglycemia-induced muscle atrophy is suppressed." (PMID 39693147, 2024).
osteosarcoma (7 papers, 2017 to 2024). A usually aggressive malignant bone-forming mesenchymal neoplasm, predominantly affecting adolescents and young adults. "One group reported that WWP1 expression was associated with single-nucleotide polymorphisms (SNPs) and copy number variants (CNVs) in osteosarcomas." (PMID 34226507, 2021). "Moreover, deficiency of WWP1 triggered G1 phase arrest and cell apoptosis in osteosarcoma cells." (PMID 34226507, 2021). "Knockdown of WWP1 significantly inhibits the growth and invasion of osteosarcoma cells, leading to G1 phase arrest and apoptosis." (PMID 39062505, 2024). "The expression of WWP1 in osteosarcoma tissues is markedly higher than in their matched normal bone tissues." (PMID 39062505, 2024). "WWP1 also promotes osteosarcoma invasion by decreasing the expression of MMPs and β-Catenin and upregulating E-Cadherin (Fig. 5C3,)." (PMID 38129384, 2023). "Mechanistically, downregulation of WWP1 regulated the expression of Bcl-2 and Bax to govern apoptosis in osteosarcoma cells." (PMID 34226507, 2021). "For example, WWP1 silencing in two osteosarcoma cell lines promoted apoptosis and reduced cell invasion." (PMID 33869064, 2021). "With research that implicates WWP1 in prostate and osteosarcoma, it is critical that additional studies be conducted to investigate possibilities of modulating the activity of WWP1 to elicit specific anti-cancer responses in the cell." (PMID 33869064, 2021). "WWP1 promotes the invasion of osteosarcoma cells and inhibits apoptosis." (PMID 39949609, 2024). "Similarly, WWP1 expression was higher in osteosarcoma tissues compared with matched normal bone tissues." (PMID 34226507, 2021). "Finally, a recent paper demonstrated that interference of WWP1 led to the induction of apoptosis in osteosarcoma cells, which is also consistent with apoptosis experiments which we performed at the characterization stage." (PMID 29518962, 2018). "RNAi-mediated WWP1 depletion results in cell cycle arrest at G0/G1 or G2/M phase in HCC, osteosarcoma, CSCC, and AML, suggesting that WWP1 can enhance cell proliferation by accelerating cell cycle progression." (PMID 38129384, 2023). "In line with the oncogenic role of WWP1, depletion of WWP1 by siRNA reduced growth and invasiveness of MG63 and HOS osteosarcoma cells." (PMID 34226507, 2021). "WWP1 also affected the expression of β-catenin, E-cadherin, MMP-2, and MMP-9, leading to regulating invasion of osteosarcoma cells." (PMID 34226507, 2021). "Furthermore, WWP1 prevents apoptosis by regulating BCL2 and BAX protein levels in osteosarcoma." (PMID 38129384, 2023).
diabetes (6 papers, 2022 to 2025). "WWP1 is implicated in various human diseases, including neurological disorders, infectious diseases, diabetes, and cardiac atrophy." (PMID 40280416, 2025). "CMT is a progressive disease, and elevated blood glucose levels associated with diabetes mellitus may further reduce muscle mass through the action of two proteins, WWP1 and KLF15." (PMID 40951209, 2025). "Altogether, both chicken MD- associated mutations in WWP1 and diabetes--associated downregulation of WWP1 could lead to skeletal muscle atrophy." (PMID 38129384, 2023). "On the basis of our results, we anticipate that co-treatment of inhibition of WWP1 expression and Adrb3 agonists will become a novel treatment for catecholamine resistance of obesity and diabetes." (PMID 40362456, 2025).
melanoma (6 papers, 2020 to 2024). A malignant, usually aggressive tumor composed of atypical, neoplastic melanocytes. "Although these findings underscore the potential involvement of WWP1 in melanoma, further experimental validation is necessary to establish a causal relationship between WWP1 expression and melanoma progression." (PMID 39949609, 2024). "In melanoma, WWP1 mediates the K48-linked ubiquitination and degradation of KLF5, a process antagonized by oncogenic deubiquitinase BAP1." (PMID 38129384, 2023). "In melanoma patients, the expression level of WWP1 was positively associated with good prognosis whereas the expression levels of KLF5 and BAP1 were found to be positively associated with poor prognosis." (PMID 36918822, 2023). "Poor expression of WWP1 was observed in melanoma cells and melanoma tissues, which was associated with poor prognosis in melanoma patients." (PMID 34226507, 2021). "Subsequent investigations showed that WWP1 overexpression in melanoma cells could mediate K48-linked ubiquitination of KLF5 and induce its proteasomal degradation, whereas BAP1 overexpression reverted this modification and increased KLF5 protein expression." (PMID 36918822, 2023). "WWP1 targets KLF5 for degradation via K48-linked ubiquitination in melanoma cells." (PMID 34226507, 2021). "Jia and colleagues found that BAP1 promotes melanoma migration and invasion by antagonizing WWP1-mediated KLF5 ubiquitination and degradation, suggesting that WWP1 plays a negative role in regulating invasion and migration in melanoma." (PMID 38129384, 2023). "WWP1 inhibits the proliferation, migration and invasion of melanoma." (PMID 39949609, 2024). "Studies have shown that WWP1 is underexpressed in melanoma, where KLF5 levels are elevated." (PMID 39949609, 2024). "Ubiquitin-mediated degradation of oncoprotein KLF5 by WWP1 could induce autophagy signaling, thereby inhibiting melanoma cell malignant phenotypes in vitro as well as progression and metastasis of melanoma in vivo." (PMID 36918822, 2023). "WWP1 also shows the pro-autophagic and tumor suppressive activities in melanoma cells through mechanisms remaining unknown yet." (PMID 36918822, 2023). "Studies on various melanoma cell lines (CRL-2208, HTB-65, ACC236) reveal low WWP1 expression alongside high KLF5 levels, which correlate with poor prognosis." (PMID 39949609, 2024). "BAP1 counteracts WWP1-mediated KLF5 ubiquitination, promoting melanoma development by stabilizing KLF5 within the BAP1/HCF-1 complex." (PMID 39949609, 2024). "BAP1 blocked WWP1-induced degradation of KLF5 and led to upregulation of KLF5 and promoting melanoma development." (PMID 34226507, 2021). "Further studies are necessary to elucidate whether MTII regulates the expression or activities of src/casein kinase 2 or ubiquitin ligases (such as WWP1 and WWP2), thereby modulating PTEN expression in melanoma cells." (PMID 31968661, 2020).